CD37 (CD37 molecule)
Diseases named in the same sentence as CD37 in open-access papers (continued):
Sharing a sentence is not in itself a finding about the gene and the disease.
glioma (2 papers, 2020 to 2025). A benign or malignant brain and spinal cord tumor that arises from glial cells (astrocytes, oligodendrocytes, ependymal cells). "CD37, another gene in the cluster, was upregulated in IDH wild-type gliomas and linked to poor prognosis." (PMID 41007824, 2025). "Through high-throughput expression profiling, WGCNA, lasso, and multivariate Cox analysis, we acquired eight genes (HCK, HAVCR2, CD37, LPAR5, NAGA, C1QC, FCER1G and AIF1) to construct the MRGs signature in Grade II/III glioma patients." (PMID 33186124, 2020).
mantle cell lymphoma (2 papers, 2021 to 2024). Mantle cell lymphoma is a rare form of malignant non-Hodgkin lymphoma affecting B lymphocytes in the lymph nodes in a region called the ``mantle zone''. "High CD37 expression was also confirmed in patient derived xenografts (PDX) of mantle cell lymphoma, CLL, and PTCL by flow cytometry and immunohistochemistry." (PMID 34332618, 2021). "CD37, encoding a protein member of the transmembrane 4 superfamily, also known as the tetraspanin family, is associated with osteogenesis imperfecta, III-type, and mantle cell lymphoma, playing a critical role in regulating tumor onset and progression." (PMID 39108264, 2024). "The CD37 CAR-T cells were as effective as CAR19 in Jeko and PDX model of mantle cell lymphoma." (PMID 34332618, 2021).
atherosclerosis (1 paper, 2024). A disease characterized by the build-up of fatty material and calcium deposition in the arterial wall resulting in partial or complete occlusion of the arterial lumen. "Many studies have shown that CD37 is an enemy of atherosclerosis." (PMID 39735551, 2024).
atopic dermatitis (1 paper, 2023). "The expression of the tetraspanins such as CD9, CD37, CD53, CD63, CD81, and CD82 on FcεRIpos skin dendritic cells (DCs) from atopic dermatitis patients is significantly higher when compared to skin DCs of not allergic healthy individuals." (PMID 36672710, 2023).
B-cell neoplasm (1 paper, 2021). A group of heterogeneous lymphoid tumors generally expressing one or more B-cell antigens or representing malignant transformations of B-lymphocytes. "Based on these promising preclinical data, an early phase clinical trial was opened to explore the CD37 CAR-T cells for CD37+ hematologic malignancies, including mature B cell neoplasms, mature T cell neoplasms, and T-cell or B-cell prolymphocytic leukemia (NCT04136275)." (PMID 34332618, 2021).
brain cancer (1 paper, 2020). A primary or metastatic malignant neoplasm affecting the brain. "We found that CD37 gene is hypermethlated in germ cell cancer, but hypomethlated in testicular germ cell tumors, kidney renal clear cell carcinoma, type 2 diabetes and brain cancer ganglioneuroma." (PMID 32400873, 2020).
COVID-19 (1 paper, 2021). A disease caused by infection with severe acute respiratory syndrome coronavirus 2. "We also found an increased expression of CD63, ITGB2, CD37, CD2 and IL23R markers and the reduction in CXCR4, CD69, CD48, ICAM1 and S100A10 markers in COVID-19-derived NK-T cells compared to controls." (PMID 34944610, 2021).
diabetes mellitus (1 paper, 2023). A metabolic disorder characterized by abnormally high blood sugar levels due to diminished production of insulin or insulin resistance/desensitization. "This could be interpreted as a contradictory finding, as hyperglycaemia was shown to increase parasitaemia and mortality in an animal model of acute CD37 and patients with diabetes mellitus are known to have increased susceptibility to infection, which is linked to immune dysfunction." (PMID 38126526, 2023).
glioblastoma (1 paper, 2022). The most malignant astrocytic tumor (WHO grade IV). "The CD37 enzyme is overexpressed on the glioblastoma cell surface and increases adenosine synthesis, which is responsible for cancer cell proliferation and invasion." (PMID 36358663, 2022). "In addition, the designed CD37-siRNAs LNPs were detected in the brain of the glioblastoma-bearing Wistar rats upon intranasal administration, demonstrating the prepared nanoemulsion’s capacity to pass the BBB." (PMID 36358663, 2022).
glomerulosclerosis (1 paper, 2023). A hardening of the kidney glomerulus caused by scarring of the blood vessels. "The mRNA Cd37 is a molecule that is expressed on the surface of B cells, and it is reported to be involved in the development of immunoglobulin A nephropathy with renal fibrosis and glomerulosclerosis in Cd37-deficient mice." (PMID 38132237, 2023). "It is necessary to further investigate the mechanism by which Cd37 may suppress renal fibrosis and glomerulosclerosis." (PMID 38132237, 2023).
melanoma (1 paper, 2021). A malignant, usually aggressive tumor composed of atypical, neoplastic melanocytes. "CD39 and CD37 are both expressed on infiltrating immune cells and CD39 is also expressed on melanoma cells and Treg." (PMID 34356899, 2021).
myeloid leukemia (1 paper, 2024). A clonal proliferation of myeloid cells and their precursors in the bone marrow, peripheral blood, and spleen. "When the anti-CD37 antibody M-B371 was used on the pro-monocytic myeloid leukemia cell line, U-937, a negative-to-weak signal was observed." (PMID 38754420, 2024).
Nephropathy (1 paper, 2017). A nonspecific term referring to disease or damage of the kidneys. "In addition, elevated serum IgA levels in the absence of CD37 led to glomerular IgA deposition and increased levels of inflammatory phagocytes within the kidney, making cd37−/− mice prone to spontaneous nephropathy." (PMID 29201860, 2017).
pancreatic ductal adenocarcinoma (1 paper, 2024). An infiltrating adenocarcinoma that arises from the epithelial cells of the pancreas. "For pancreatic ductal adenocarcinoma, the CD37-dependent adenosine pathway inhibits immune cells, leading to immune suppression and implicating that products of the nucleotide metabolism pathway function as immune regulators and promote cancer immuno-surveillance." (PMID 39715885, 2024).
peripheral T cell lymphoma (1 paper, 2020). "While CD37 is predominantly being examined for dual targeting for B cell malignancies, the expression of CD37 in some cases of CTCL and peripheral T cell lymphoma (PTCL) makes it an attractive target in these malignancies, otherwise difficult to treat with CAR-T cell-based therapies." (PMID 33333768, 2020).
Salmonella Infections (1 paper, 2020). Infections with bacteria of the genus SALMONELLA. "Pathway analysis data showed that CD37 is involved in DNA replication, RNA transport, Salmonella infection, ribonucleoprotein complex biogenesis, cell cycle phase transition and so on." (PMID 32400873, 2020).
synovial sarcoma (1 paper, 2017). "Therefore, although the “gold standard” for synovial sarcoma is molecular testing, TLE1-targeted therapeutics could be used to selectively treat synovial sarcoma without damaging host tissue and could be a useful immunohistochemical marker in combination with CD37, CK7, EMA, BCL2, and MIC2." (PMID 27852056, 2017).
tumor (50 papers, 2009 to 2026). "After humanization using CDR-grafting, antibodies were expressed in a human IgG1 backbone with and without the E430G hexamerization-enhancing mutation (Hx) and binding to CD37 on human tumor cells was assessed using Daudi cells." (PMID 32341336, 2020). "This was caused by an impaired T cell-driven anti-tumour immune response due to migration failure of CD37-deficient DCs." (PMID 32451606, 2020). "DuoHexaBody-CD37 is a biparatopic bispecific IgG1 antibody with a hexamerization-enhancing mutation that induces strong anti-tumor activity in preclinical models in vitro and in vivo through potent CDC, ADCC and ADCP." (PMID 32341336, 2020). "Mice deficient for CD37 are more susceptible to infection with murine malaria and fail to reject syngeneic tumor cells transfected to express a foreign antigen." (PMID 25852576, 2015). "However, despite the fact that AML could be characterized as a disease with low tumor mutational burden, more extensive analysis could be undertaken to exclude the presence of CD37 mutations in AML patients." (PMID 38754420, 2024). "Therefore CD37-deficiency in mice leads to impaired tumor rejection." (PMID 33333768, 2020). "The extent of tumor infiltration was comparable between CD37−/− and CD37fl/fl mice, and the survival duration was similar in both groups." (PMID 40250439, 2025). "For example, both CD37 and RCSD1 are linked to recruitment of anti-tumour immune cells and improved prognoses." (PMID 38902676, 2024). "One potential concern with targeting CD37 is off-tumor expression on monocytes, raising the prospect of on-target/off-tumor toxicity." (PMID 39095991, 2024). "We previously reported that ∼60% of patients with aggressive DLBCL have aberrant CD37 expression in tumour tissues which is related to inferior clinical outcome." (PMID 36100608, 2022). "We showed that [89Zr]Zr-N-sucDf-NNV003 accumulated in REC1 and RAMOS tumor tissues in a CD37-dependent manner, resulting in high tumor-to-blood ratios." (PMID 35428777, 2022). "Ex vivo [89Zr]Zr-N-sucDf-NNV003 tumor uptake was higher compared to [111In]In-DTPA-IgG for all protein dose groups, confirming that [89Zr]Zr-N-sucDf-NNV003 tumor uptake is CD37-mediated." (PMID 35428777, 2022). "[89Zr]Zr-N-sucDf-NNV003 tumor uptake was comparable for REC1 and RAMOS tumors, with both tumor types expressing similar levels of CD37 as measured by flow cytometry and immunohistochemistry." (PMID 35428777, 2022). "The function of CD37 is not fully understood, but researches indicated that CD37 was involved in immune regulation and tumor supression." (PMID 34256851, 2021). "CD37-CAR demonstrated profound anti-tumor activity in a range of B-cell lymphoma cell lines and in patient-derived MCL xenograft (PDX) models in NSG mice." (PMID 34203935, 2021). "At first, we tested the efficacy of CD37-CAR-T cells in vivo and performed survival analysis using a Raji-xenograft tumor model after an injection of mouse CD37-CAR-T cells and humanized CD37-CAR-T cells." (PMID 33652767, 2021). "Together, these observations identify CD37 as a tumor suppressor that directly protects against B cell lymphomagenesis." (PMID 33333768, 2020). "CD37 has a bivalent role in the phosphatidylinositol 3′-kinase (PI3K)/AKT survival pathway in tumor suppression and in humoral immunity." (PMID 31836849, 2020). "Collectively, these data indicate that DuoHexaBody-CD37 can mediate significant anti-tumor activity in both CDX and PDX in vivo models derived from different B-cell malignancy subtypes." (PMID 32341336, 2020). "Together, these data demonstrate that DuoHexaBody-CD37 induces efficient FcγR-mediated immune effector functions to kill CD37-positive tumor cells." (PMID 32341336, 2020). "Three weekly doses of DuoHexaBody-CD37 resulted in significantly reduced tumor growth in the Daudi-Luc model at all tested dose levels as compared to the IgG1-ctrl, and at 1 and 10 mg/kg in the JVM-3 and DOHH-2 models." (PMID 32341336, 2020).
tumor (continued). "The potent anti-tumor activity exhibited by DuoHexaBody-CD37 in preclinical B-cell malignancy models highlights its therapeutic potential." (PMID 32341336, 2020). "Follow-up cohort studies in two responding PDX models (Ly12638 and Ly13005) confirmed potent, dose-dependent anti-tumor activity of DuoHexaBody-CD37 at doses as low as 1 mg/kg." (PMID 32341336, 2020). "The promising preclinical results with DuoHexaBody-CD37 have demonstrated its improved efficacy in terms of engaging different mechanisms of the immune response against the tumor." (PMID 33333768, 2020). "The efficacy of DuoHexaBody-CD37 in repressing tumor growth has been demonstrated in xenograft models as well as in B-NHL patient-derived xenografts (PDX)." (PMID 33333768, 2020). "In a screening approach, we evaluated the anti-tumor efficacy induced by DuoHexaBody-CD37 using nine NHL PDX models in an experimental set up using a one mouse per group design." (PMID 32341336, 2020). "A high uptake of 177Lu-NNV003 in CD37-expressing tumours compared to normal organs and blood was observed." (PMID 31309259, 2019). "In the reactive astrocytes from the tumor we identified an increased expression of immune associated genes such as CHI3L1, HLA-DRA, CD274, HLA-DRB3, CD37, as well as genes that contributed to proliferation (MKI67, ANXA2) and complement components (C1S, C1R)." (PMID 31186414, 2019). "CD37−/− mice challenged with two different doses of an immunogenic tumor showed defective tumor rejection compared to wild-type (WT) mice, indicating that CD37 is directly involved in antitumor immunity." (PMID 29896201, 2018). "This final broad category of therapies utilizes anti-CD37 antibodies to guide cytotoxic agents to tumor cells." (PMID 25852576, 2015). "Additionally, 212Pb, a β-to-α generator, is being explored for its potential in treating NHL, especially with its ability to target CD22- and CD37-expressing tumor cells." (PMID 40227793, 2025). "CD37 serves as a significant immune marker in various immune cells (e.g., T cells, B cells, and macrophages), with high expression possibly indicating adequate filtration and immune competence in the tumor microenvironment." (PMID 39108264, 2024). "Furthermore, a combination of antibodies targeting CD37 (IgG1-CD37.3-RGE) and CD20 (IgG1-11B8-AGK) induced potent and mutually dependent CDC on a CD37+CD20+ tumor cell line." (PMID 35879362, 2022). "Additionally, 212Pb-NNV003, a CD37-targeted radioimmunotherapy, has demonstrated notable anti-tumor effects in an animal model of CLL." (PMID 33683501, 2021). "Additionally, more infiltration of active T cells (CD3+ and CD37+T cell) into the tumour tissues and their co-localisation with CD3+T cells were observed after treatment with NRT cells than in conventional T cell-treated mice." (PMID 34291357, 2021). "Scatchard analysis confirmed CD37 expression in the tumor cell lines used for this study." (PMID 31836849, 2020). "Similar to CD20, CD37 is highly expressed on tumor B cells across all major NHL and CLL subtypes." (PMID 32341336, 2020). "We hereby report the generation of a panel of CD37-targeting mAbs with an E430G hexamerization-enhancing mutation and characterized the preclinical mechanism of action and anti-tumor activity of the single mAbs, mAb combinations and CD37 biparatopic (bispecific) antibodies." (PMID 32341336, 2020). "One study reported increased tumour growth in Cd37 knock-out mice." (PMID 32451606, 2020). "Furthermore, in xenograft models in vivo, DuoHexaBody-CD37 induced significant inhibition of tumor growth in a CLL CDX model, two NHL CDX models and six out of nine NHL PDX models." (PMID 32341336, 2020). "In this context, Yuh-Ying Yeh and co-workers have identified the tetraspanin, CD9, CD63, and CD37 as abundantly expressed markers in tumor exosomes of CLL patients by flow analysis and immunoblotting, in contrast to the modest expression of CD41, CD56, and CD3." (PMID 32759810, 2020).
tumor (continued). "The higher uptake in MEC-2 tumours than in DOHH-2 tumours, even though the CD37 expression was similar, might be explained by higher degree of 177Lu-NNV003 internalisation in MEC-2 cells (Online Resource)." (PMID 31309259, 2019). "Rituximab-coated Raji tumor cells were then labeled with mouse anti-human CD37 antibody (a B cell-specific cell surface marker) followed by goat anti-mouse Alexa Fluor 594 (red fluorescence) and IFNγ primed macrophages were stained with FITC-phalloidin (green fluorescence)." (PMID 19148288, 2009). "Additionally, novel in vitro studies suggest that combining CD37-TRT with PARP inhibitors could enhance therapeutic efficacy by increasing tumor radiosensitivity via DNA damage response inhibition." (PMID 40227793, 2025). "Since patients are at risk for developing hematological toxicities due to CD37 expression on normal B cells, we aimed to develop 89Zr-labeled NNV003 for positron emission tomography (PET) imaging as a surrogate tool to predict [177Lu]Lu-DOTA-NNV003 RIT whole-body distribution and tumor uptake." (PMID 35428777, 2022). "Furthermore, a post-therapy [89Zr]Zr-N-sucDf-NNV003 scan may inform on therapy response by evaluating CD37-mediated tumor uptake after [177Lu]Lu-DOTA-NNV003 RIT." (PMID 35428777, 2022). "Consequently, the threshold for complement activation by DuoHexaBody-CD37 might be lower, which could result in enhanced anti-tumor efficacy in clinical settings." (PMID 32341336, 2020). "While lymphoid aggregates alone did not distinguish between responsive and non-responsive tumours, the integrated analysis revealed higher expression of genes like CD37, MS4A1, BLK, CD79A/B, and TNFRSF13C in responsive tumours’ lymphoid aggregates." (PMID 40141092, 2025). "Mice transplanted with CD37−/− LSCs exhibited a marked reduction in AML progression, accompanied by reduced tumor infiltration and prolonged survival, compared to those transplanted with CD37fl/fl LSCs." (PMID 40250439, 2025). "The outcomes revealed that the levels of CD37, GABRD and ARHGAP25 were significantly elevated in the tumor cells than that in the normal cell line." (PMID 37465666, 2023). "PET quantification showed [89Zr]Zr-N-sucDf-NNV003 accumulation in CD37-expressing RAMOS tumors for all tested protein doses, with the highest tumor-to-blood ratios found for day 5 pi." (PMID 35428777, 2022). "CD37 CAR-Ts have been explored in preclinical models with signs of activity, but the potential for on-target off-tumor toxicity to CD37+ immune cells remains an important consideration." (PMID 34680329, 2021). "Naratuximab emtansine demonstrated high anti-tumor activity when investigated in models of CLL and CD37-positive NHL in preclinical studies." (PMID 33333768, 2020). "In addition, DuoHexaBody-CD37 showed significant anti-tumor efficacy in vivo in human cell line- and patient-derived xenograft models, indicating that DuoHexaBody-CD37 may serve as a promising novel therapeutic antibody for treatment of human B-cell malignancies." (PMID 32341336, 2020). "While the primary rationale behind the development of DuoHexaBody-CD37 was focused on maximizing its capacity to induce CDC, other Fc-mediated effector functions such as ADCC and ADCP, known to contribute to tumor cell kill, were also tested." (PMID 32341336, 2020). "In the current study, a novel anti-CD37 TAT 212Pb-NNV003 induced cytotoxicity in cell lines and was rapidly taken up in CD37 positive tumours." (PMID 32187209, 2020). "CD19 CAR, CD37 CAR, and CD19/CD37 CAR were equally effective in tumor eradication in a xenograft MCL model." (PMID 33333768, 2020). "DuoHexaBody-CD37 induced potent CDC in 8 of the 16 cell lines tested, with generally higher levels of tumor cell lysis observed in cell lines with CD37 expression levels above 100,000 copies/cell." (PMID 32341336, 2020). "We identified an increased expression of genes that were previously found in the astrocytes from tumor specimens, (HLA-DRA, CHI3L1 SERPINA1, CCL18, CD37, and CD274)." (PMID 31186414, 2019).